PRL (prolactin)
Diseases named in the same sentence as PRL in open-access papers (continued):
Sharing a sentence is not in itself a finding about the gene and the disease.
Insulin resistance (143 papers, 2006 to 2026). Increased resistance towards insulin, that is, diminished effectiveness of insulin in reducing blood glucose levels. "Studies have shown that hypoglycemic stress leads to a transient increase in PRL, and low levels of PRL are associated with insulin resistance." (PMID 40964426, 2025). "In contrast, disturbances in mid-to-late pregnancy are associated with elevated levels of placental prolactin and placental growth hormone, along with insulin resistance." (PMID 39861387, 2025). "Obesity is also linked to diverse endocrine dysregulations, including insulin resistance and decreased prolactin activity." (PMID 39857075, 2025). "A logistic regression analysis was further conducted to evaluate the associations between the increased prolactin levels and relative risk for the overweight/obesity, insulin resistance and prediabetes in the studied women with PCOS." (PMID 40362476, 2025). "Insulin resistance parameters associated with the metabolic syndrome, cortisol, PRL, LH, and testosterone concentrations play a predictive role in the development of depression and anxiety." (PMID 39519542, 2024). "In women with PCOS, an association of prolactin levels > 14.9 ng/mL with a decreased incidence of insulin resistance had been previously demonstrated according to a recent review." (PMID 39768704, 2024). "Conversely, lower levels of PRL were observed to associate with insulin resistance and adipocyte hypertrophy in the visceral adipose tissue of overweight and obese individuals." (PMID 38760578, 2024). "MetS development is affected by endocrine hormones such as prolactin (PRL) hormone which induce insulin resistance and central obesity because PRL is implicated in the pathogenesis of MetS." (PMID 39663784, 2024). "Particularly, PRL values above 100 ng/ml have been proposed to be associated with an increased prevalence of obesity, glucose intolerance, insulin resistance and metabolic syndrome." (PMID 39078526, 2024). "For example, despite strong support for the role of PRL in promoting insulin secretion in pregnancy, several studies show that high levels of PRL are associated with insulin resistance and/or hyperglycaemia, beta cell dysfunction and risk of GDM." (PMID 37049394, 2023). "Prolactin (PrL) and placental lactogen (PL) have been implicated in pregnancy-associated β-cell adaptations, as well as in peripheral insulin resistance and increased lipolysis." (PMID 36836658, 2023). "Patients with low circulating PRL levels have hypertrophic visceral adipocytes and are associated with increased insulin resistance." (PMID 36993818, 2023). "Other potential PMS-triggering factors include genetic factors, electrolyte deficiency, insulin resistance, improper hypothalamic–pituitary–adrenal axis activity, abnormal glucose metabolism, and elevated prolactin." (PMID 38131720, 2023). "Some studies report that “excessive prolactin levels have been associated with insulin resistance in diabetes”, and some report that “high prolactin levels are associated with decreased risk of diabetes mellitus and impaired glucose tolerance”." (PMID 34055923, 2021). "Abnormal glucose tolerance in pregnancy is mainly caused by increased insulin resistance due to placenta-derived factors such as lactogen and prolactin, obesity, and inhibition of insulin signaling." (PMID 33776619, 2021). "Elevated prolactin levels, concomitant antidepressant, increased insulin resistance, longer illness duration, and female sex were associated with sexual dysfunction." (PMID 34421613, 2021). "Insulin resistance caused by prolactin located in the human placenta introduces recession of the LPL activity and improved lipolysis of the adipose tissue." (PMID 35126125, 2021). "Roles of prolactin on both insulin resistance and decreased insulin secretion (i.e., inverse association with C-peptide levels) are consistent with our finding of a positive association between prolactin and GDM risk." (PMID 32180760, 2020).
Insulin resistance (continued). "The classic view held that the antagonistic effects of prolactin, prolactin, glucocorticoid, and progesterone on insulin secretion and insulin resistance during pregnancy were the main causes of GDM." (PMID 32280713, 2020). "Regarding PRL, it was found high in women suffering from obesity and high serum PRL levels were linked to insulin resistance and increased HOMA-IR index in both men and women." (PMID 32082253, 2019). "Higher serum PRL levels within the physiological range seem to be associated with insulin resistance in men." (PMID 28384295, 2017). "It is known that increased prolactin levels in cases with prolactinoma cause obesity, insulin resistance, an increase in homocysteine levels and low-grade inflammation and subsequently a tendency to cardiovascular diseases." (PMID 21331754, 2011). "Indeed, prolactin causes a state of insulin resistance (IR) and hyperinsulinism secondary to the increase in the cell mass of the islets of Langerhans." (PMID 40426951, 2025). "Although PRL is associated with insulin resistance during pregnancy, its reduction in the exercise group may reflect improved metabolic balance and decreased inflammatory burden." (PMID 41462441, 2025). "Furthermore, low prolactin levels have been associated with impaired glucose metabolism and insulin resistance, both of which are important risk factors for the development of type 2 diabetes." (PMID 38826895, 2024). "As pregnancy progresses, the upregulation of human placental lactogen (hPL), estrogen, progesterone, cortisol, and prolactin can cause progressive insulin resistance, and when pancreatic β-cells fail to compensate for the situation, it will lead to hyperglycemia and even gestational diabetes." (PMID 39777224, 2024). "Accordingly, patients with lower baseline prolactin levels might benefit more from metformin treatment in terms of insulin resistance, although these associations were rather weak." (PMID 39768704, 2024). "This suggests that maternal obesity post-FA fortification may increase the risk of insulin resistance due to low PRL and hPL in the setting of higher GH2." (PMID 37049394, 2023). "Interestingly enough, there are literature data associating PRL with insulin resistance, hyperglycemia, and weight gain, contributing indirectly to CVD risk." (PMID 36704037, 2022). "Hyper-PRL may be associated with insulin resistance and glucose intolerance in participants with PCOS." (PMID 35098010, 2021). "In addition, as an insulin resistance-related risk factor, serum PRL levels were found to have an inverse association with WC, similar to results for PCOS or hypertrichosis patients." (PMID 33716958, 2021). "Moreover, low serum PRL levels are associated with an increased prevalence of type 2 diabetes, insulin resistance, glucose intolerance, and fatty liver in the clinic." (PMID 33746901, 2021). "Therefore, PRL has been suggested to be closely associated with insulin resistance, hypertension, thrombembolia, stroke and coronary syndrome." (PMID 32477263, 2020). "Because weak effects of metformin were observed in euthyroid Hashimoto’s thyroiditis, while thyroid hypofunction, independently of its cause, often results in prolactin excess and insulin resistance, individuals with untreated autoimmune hypothyroidism may be poor candidates for metformin treatment." (PMID 37297964, 2023). "When PRL concentrations are low within the physiologic range, adiponectin production is down-regulated, which causes an inflammatory state that might increase insulin resistance and decrease insulin sensitivity." (PMID 36471299, 2022). "This heterogeneity could result in different patterns of metabolic features associated with PCOS that might affect PRL levels, including differences in the secretion of dopamine and melatonin, as well as differences in the prevalence of obesity and insulin resistance." (PMID 36552931, 2022).
Insulin resistance (continued). "Hence, we deduce that low prolactin levels within the normal range may be associated with increased WC and HC and a higher risk for insulin resistance." (PMID 33716958, 2021). "Beyond its role in lactation, prolactin plays a diverse role in several physiological processes, including insulin resistance, metabolic syndrome, inflammation, endothelial dysfunction, and atherosclerosis." (PMID 40021736, 2025). "Our study shows that women with folate excess had higher hPL and PRL (both primarily promote insulin secretion, although hPL has also been reported to promote insulin resistance) compared to women whose folate was within the normal range." (PMID 40944254, 2025). "Serum prolactin, BMI, complete glucose-insulin profile and insulin resistance indices following OGTT were determined." (PMID 40362476, 2025). "In conclusion, in overweight/obese, insulin-resistant PCOS women, lower baseline prolactin levels are associated with higher baseline HOMA-IR levels as well as with a better response to metformin treatment." (PMID 39768704, 2024). "Metabolic diseases such as T2D, insulin resistance, and adipose tissue dysfunction course with low systemic PRL levels, whereas PRL administration improves insulin sensitivity and decreases adipocyte hypertrophy in HFD-induced obese male rats." (PMID 38635745, 2024). "Insulin resistance and metabolic syndrome parameters, cortisol, PRL, and LH concentrations were positive predictors for depression and anxiety prior to intervention, while testosterone was a negative predictor before and after the intervention." (PMID 39519542, 2024). "Treatment of diabetic rats with low-dose PRL increased β-cell mass and improved hepatic insulin resistance, whilst high-dose PRL treatment led to whole-body insulin resistance." (PMID 38760578, 2024). "Several studies attributed systemic insulin resistance during gestation to the rising levels of lactogenic hormones such as prolactin (PRL) and human placental lactogen (hPL)." (PMID 39035597, 2024). "Regarding hormonal factors, cortisol, prolactin, and placental lactogen worsen P4-induced insulin resistance during pregnancy." (PMID 38539988, 2024). "Insulin resistance and metabolic syndrome parameters, cortisol, PRL, and LH concentrations were positive predictors for depressive and anxiety symptoms." (PMID 39519542, 2024). "The model links PRL levels with reduced insulin resistance, improved glucose tolerance, decreased adipose tissue hypertrophy, and a protective effect against metabolic syndrome and diabetes type two development." (PMID 39857650, 2024). "In contrast, in the interval between these two extremes, prolactin seems to have a protective effect against the development of insulin resistance and consequently diabetes mellitus." (PMID 39425884, 2024). "In our interactome, it is implicated in insulin resistance, FPT, and prolactin signaling non-alcoholic fatty liver (NAFL) pathways." (PMID 39457593, 2024). "For the KEGG database, the affected pathways included insulin signaling pathway, insulin resistance, prolactin signaling pathway, estrogen signaling pathway, circadian rhythm, endocrine resistance, oxytocin signaling pathway, and MAPK signaling pathway." (PMID 39564184, 2024). "Because elevated prolactin levels are a risk factor for insulin resistance and glucose abnormalities, a stronger effect of metformin on glucose homeostasis markers in individuals with prolactin excess may be explained by differences in post-treatment prolactin levels." (PMID 37297909, 2023). "On the other hand, PRL excess in supraphysiologic levels result in increase of HOMA-IR(surrogate index of insulin resistance), in both obese and lean patients." (PMID 36993818, 2023). "GH2 promotes maternal insulin resistance, whereas PRL promotes insulin secretion to compensate for the increase in maternal insulin resistance during pregnancy." (PMID 37049394, 2023).
Insulin resistance (continued). "Therefore, some authors hypothesized that upregulation of PRL levels is a mechanism to maintain metabolic homeostasis and proposed that either very low levels of PRL (< 7 ng/mL) or higher levels of PRL (> 100 ng/mL) were associated with insulin resistance and metabolic syndrome." (PMID 36704037, 2022). "In contrast, mice receiving high prolactin doses had a mean prolactin level of 205.3 +/- 6.8 ng/mL with increased insulin resistance and impaired glucose tolerance." (PMID 36246929, 2022). "In high prolactin states, central dopaminergic neurons become refractory to prolactin, contributing to weight gain and insulin resistance." (PMID 36246929, 2022). "Insulin resistance, growth hormone, prolactin, ACTH, and cortisol showed significant improvements all around at 6 months follow up, although greater tendency toward improvement in the VR group was noted per the post hoc Bonferroni test." (PMID 35295809, 2022). "The concentration of prolactin influences the relationship between prolactin and insulin resistance." (PMID 36246929, 2022). "Of them, the top 10 KEGG pathways were selected, including adipocytokine signaling pathway, insulin resistance, foxO signaling pathway, non-alcoholic fatty liver disease and prolactin signaling pathway." (PMID 35408632, 2022). "Serum PRL decreases in rodents with obesity, diabetes, and insulin resistance, suggesting a role for reduced PRL levels in the pathophysiology of metabolic diseases." (PMID 36213259, 2022). "This relative contradiction seems to indicate that a delicate balance of PRL and hPL during pregnancy is needed to achieve adequate pancreatic β-cells proliferation and to avoid insulin resistance." (PMID 34360849, 2021). "One study confirmed insulin resistance in Hyper-PRL subjects and showed the role of prolactin in mediating insulin resistance." (PMID 35098010, 2021). "In a diabetic mouse model, low- and high- PRL treatment induced β-cell proliferation; however, low PRL levels reduced hepatic insulin resistance whereas high PRL exacerbated it and elevated apoptosis of β-cells." (PMID 34360849, 2021). "It is reported that the role of PRL on glucose metabolism and insulin resistance depends on its circulating concentration." (PMID 33716958, 2021). "Treatment of obese rats with PRL improves insulin sensitivity and challenging global Prlr null mice with an obesogenic diet exacerbates insulin resistance and glucose intolerance." (PMID 33746901, 2021). "The lactotroph hormones prolactin (PRL) and human placental lactogens participate in cell-specific β-cell responses to counteract the physiological insulin resistance developed during pregnancy." (PMID 34360849, 2021). "Insulin resistance, hypogonadism, prolactin levels, body mass index, and tumor size all improved by regular follow-up and treatment adherence." (PMID 34095489, 2021). "Higher prolactin levels, concomitant antidepressant, greater insulin resistance indices, longer duration of illness, and female sex were associated with sexual dysfunction." (PMID 34421613, 2021). "During pregnancy, increased insulin resistance in the mother promotes nutrient transfer to the fetus through blood flow, whereas maternal β-cell expansion is induced by prolactin (PRL) and placental lactogen to compensate for the increased insulin resistance." (PMID 32188885, 2020). "Another similar case-control study, this time with 31 prolactinoma patients and 60 controls, demonstrated increased carotid intima-media thickness, with increased insulin resistance, inflammation, and endothelial dysfunction in those with elevated prolactin." (PMID 32655635, 2020). "Remarkably, the low dose of EPR oil did not produce any significant effect on body weight but improved insulin resistance and reduced IL1β level beside amelioration of serum PRL, testosterone and gonadotropins." (PMID 32082253, 2019).
Insulin resistance (continued). "For elderly women, the low islet function and insulin sensitivity, the impaired function of islet beta cells and the excessive secretion of glucocorticoid, such as placental prolactin, are easy to induce insulin resistance." (PMID 30087863, 2018). "The STAT5A-mediated induction of pyruvate dehydrogenase kinase 4 expression by prolactin results in an inhibition of insulin-stimulated glucose transport in fat cells and contributes to insulin resistance." (PMID 29088862, 2017). "In contrast, four genes such as IL10RA, TLR3, FOS, and PRL demonstrate strong inverse correlations with insulin resistance." (PMID 26089598, 2015). "We observed inverse correlations between serum adiponectin level and bodymass index, homeostasis model assessment insulin-resistance score, insulin level, fast-ing glucose level, and prolactin level (p=0.001, p=0.02, p=0.04, p=0.02, and p=0.005,respectively)." (PMID 24520503, 2014). "It has also been reported that prolactin is involved in insulin resistance in WAT during lactation and suppresses insulin-induced leptin production in WAT." (PMID 24299740, 2014). "The ability of PRL to stimulate insulin and suppress adiponectin as well as interleukin-6 release further suggests a potential role in the manifestation of insulin resistance." (PMID 23517652, 2013). "According to some authors, such verification contradicts the classical concept that insulin resistance in pregnancy is exclusively induced by placental hormones such as progesterone, human chorionic gonadotropin, prolactin, and estradiol." (PMID 22462002, 2012). "The insulin resistance that develops during pregnancy is explained in part by the increased production of human placental lactogen, estrogen, and prolactin." (PMID 23029294, 2012). "Further studies detected a correlation between increasing insulin resistance and fasting insulin level, with PRL." (PMID 22405326, 2012). "Therefore, the aim of the current study was to investigate the serum levels of prolactin in women with PCOS and their associations with obesity, insulin resistance and prediabetes." (PMID 40362476, 2025). "However, there are also discrepancies in the literature about the relationship between PRL and insulin resistance in PCOS." (PMID 40362476, 2025). "Increased prolactin levels may serve as a further marker of insulin resistance in women with polycystic ovary syndrome." (PMID 40362476, 2025). "Age-related changes in endocrine function, such as altered prolactin secretion and increased insulin resistance, may exacerbate the metabolic and inflammatory disturbances associated with obesity, further impairing milk production." (PMID 40868103, 2025). "Increased prolactin levels may serve as an additional indicator of insulin resistance and even further exacerbate it in women with PCOS." (PMID 40362476, 2025). "Therefore, a correlation between elevated PRL levels and peripheral insulin resistance has been recently suggested." (PMID 40362476, 2025). "Therefore, this study aimed to investigate the serum levels of prolactin in women with PCOS and their associations with obesity, insulin resistance and prediabetes." (PMID 40362476, 2025). "Moreover, low PRL levels correlate with a higher prevalence of T2D, insulin resistance, and adipocyte hypertrophy in humans." (PMID 38635745, 2024). "Given the assumption that moderately high prolactin levels would counteract insulin resistance and glucose intolerance, patients with lower baseline prolactin levels seem to be those who are incapable of a beneficial endocrine reaction to their abnormal metabolic status." (PMID 39768704, 2024). "Dopaminergic drugs acting on the pituitary level could be considered with some potential to reduce P4-mediated insulin resistance by suppressing prolactin levels, such as cabergoline." (PMID 38539988, 2024).